OR1D5 (olfactory receptor family 1 subfamily D member 5)
Description:
Odorant receptor.
Synonyms: OR17-31; C17orf2; OR17-2
Tractability: Antibody: its Gene Ontology location is reachable by antibodies, with high confidence; UniProt places it where antibodies can reach, with medium confidence; UniProt predicts a signal peptide or a membrane-spanning region.
Gene: Protein-coding gene on chromosome 17 (3,062,669 to 3,063,607, reverse strand). Ensembl gene ENSG00000262628.
Subcellular location: Cell membrane
Pathways (Reactome):
Sensory Perception: Expression and translocation of olfactory receptors; Olfactory Signaling Pathway
Gene Ontology:
Molecular function: G protein-coupled receptor activity; olfactory receptor activity
Biological process: G protein-coupled receptor signaling pathway; sensory perception of smell; signal transduction; detection of chemical stimulus involved in sensory perception of smell
Cellular component: plasma membrane; membrane
Genetic constraint (gnomAD): Loss-of-function variants: 1 observed, 3.38 expected, observed/expected ratio (o/e) 0.3, 90% interval 0.1 to 1.35. That is too few expected variants to judge how well the gene tolerates losing a copy. Missense variants: 149 observed, 229.43 expected, observed/expected ratio (o/e) 0.65, 90% interval 0.57 to 0.74. Synonymous variants: 54 observed, 90.44 expected, observed/expected ratio (o/e) 0.6, 90% interval 0.48 to 0.75.
Homologues: Orthologues: chimpanzee OR1D5 (97% identical), pig OR1D5 (82% identical), rabbit OR1D5 (82% identical). Paralogues in human: OR1D2 (82% identical), OR7C1 (53% identical), OR7D4 (53% identical), OR1N2 (52% identical), OR7D2 (52% identical), OR7A10 (52% identical), OR7C2 (52% identical), OR1N1 (50% identical), OR7A5 (50% identical), OR7G2 (50% identical), OR7G3 (50% identical), OR7A17 (50% identical), and 116 more.
Diseases named in the same sentence as OR1D5 in open-access papers:
OR1D5 is named in the same sentence as 1 disease in open-access papers, as found by Europe PMC text mining. Sharing a sentence is not in itself a finding about the gene and the disease.
OR1D5 shares sentences with these, for which no sentence is quoted: prostate carcinoma (1 paper).